A2M (alpha-2-macroglobulin)
Diseases named in the same sentence as A2M in open-access papers (continued):
Sharing a sentence is not in itself a finding about the gene and the disease.
myocardial infarction (2 papers, 2012 to 2018). Gross necrosis of the myocardium, as a result of interruption of the blood supply to the area, as in coronary thrombosis. "Although the association between MMP-9 and alpha-2 macroglobulin has been previously reported, this is the first time that alpha-2 macroglobulin is associated with MMP-9 in the myocardial infarction setting." (PMID 22778955, 2012). "In addition, higher alpha-2-macroglobulin serum levels were indicators of cardiac complications in HIV patients and myocardial infarction in diabetic patients." (PMID 29665821, 2018).
pancreatitis (2 papers, 2013 to 2019). Inflammation of the pancreas. "The comparative analysis showed that after pancreatitis induction exosomes in plasma were enriched in a number of proteins presumably expressed by the liver (Apolipoproteins, C-reactive protein, Retinol binding protein, Alpha-2-macroglobulin...)." (PMID 31882721, 2019).
parasitemia (2 papers, 2015 to 2025). "Studies on other parasitic infections, such as Trypanosoma, also highlighted the protective role of α2M, enhancing macrophage phagocytosis and antimicrobial activity." (PMID 40853910, 2025).
Parkinson disease (2 papers, 2019 to 2024). A progressive degenerative disorder of the central nervous system characterized by loss of dopamine producing neurons in the substantia nigra and the presence of Lewy bodies in the substantia nigra and locus coeruleus. "The chaperone function of α2M has been demonstrated in vitro using a broad range of misfolded clients including denatured globular proteins and aggregation prone, intrinsically disordered substrates (e.g., Aβ peptide and Parkinson's disease-associated alpha-synuclein)." (PMID 31428227, 2019). "Nevertheless, α2M is reported to bind to a broad range of misfolded proteins including the infectious prion protein that is responsible for transmissible spongiform encephalopathies and α-synuclein, the major constituent of misfolded protein deposits in Parkinson's disease." (PMID 31428227, 2019).
Ss (2 papers, 2014 to 2020). "To determine the effect of Ss infection on systemic inflammation in T2DM, we measured the levels of acute phase proteins (α-2M, CRP, haptoglobin and SAA-1) in Ss+ and Ss− individuals." (PMID 32984066, 2020).
tuberculosis (2 papers, 2020 to 2025). A chronic, recurrent infection caused by the bacterium Mycobacterium tuberculosis. "Our results not only confirm the important role of A2M in active tuberculosis but also uncover a regulatory network involving A2M, F12, and ECM2." (PMID 41428679, 2025). "We examined the systemic levels of APPs (alpha-2-macroglobulin [⍺-2MG], serum amyloid A [SAA], C-reactive protein [CRP] and haptoglobin [Hp]) in TBL, PTB, latent tuberculosis (LTB) and healthy controls (HC) at baseline and in TBL after the completion of anti-tuberculosis treatment (ATT)." (PMID 32470023, 2020).
age (1 paper, 2021). A temporal measurement of the time period elapsed since an identifiable point in the life cycle of an organism. "In age-associated renal fibrosis, α2M was increased in both glomeruli and the tubulointerstitium." (PMID 34572299, 2021).
allergic rhinitis (1 paper, 2020). Inflammation of the nasal mucous membranes caused by an IgE-mediated response to external allergens. "C3, A2M, APOA1, and APOA2 were also found to be significantly more abundant in nasal mucus in allergic rhinitis patients in our previous studies." (PMID 32266843, 2020).
atherosclerosis (1 paper, 2020). A disease characterized by the build-up of fatty material and calcium deposition in the arterial wall resulting in partial or complete occlusion of the arterial lumen. "The obtained results were correlated with the expression level of platelet and megakaryocyte transcripts for APOA1 and A2M genes encoding atherosclerosis biomarkers: apolipoprotein A1 (ApoA1) and α-2-macroglobulin (α2M), respectively." (PMID 33086557, 2020). "Several biomarkers and atherosclerosis imaging measures have been evaluated for association with an incident of cardiovascular disease, including apolipoprotein A1 (ApoA1) and α-2-macroglobulin (α2M)." (PMID 33086557, 2020). "α2M is a highly abundant serum protein involved in the development of atherosclerosis; however, its circulating concentrations in human health/diseases are not exactly known." (PMID 33086557, 2020). "The A2M gene expression modulates the severity and extent of atherosclerosis." (PMID 33086557, 2020).
bacterial sepsis (1 paper, 2020). "We have previously reported that alpha-2-macroglobulin loaded microparticles enhance host responses to infection by promoting neutrophil recruitment and clearance of bacteria whilst stimulating pro-resolving pathways, thus promoting a swift resolution of bacterial sepsis." (PMID 33133087, 2020).
brain injury (1 paper, 2020). Acute and chronic (see also brain INJURIES, CHRONIC) injuries to the brain, including the cerebral hemispheres, CEREBELLUM, and brain STEM. "However, the role of alpha-2-macroglobulin in modulating the proteolytic activity of thrombin and thereby ICH-induced brain injury is yet to be defined." (PMID 32170712, 2020).
cerebellar degeneration (1 paper, 2009). Degeneration of the cerebellum. "In this case, Dpl retains its capability of binding to α2M and thus of triggering cerebellar degeneration." (PMID 19536284, 2009).
Chagas disease (1 paper, 2022). A parasitic infection caused by Trypanosoma cruzi. "In a study conducted on children under 13 years of age in the acute phase of Chagas disease in an endemic area of Bolivia, a significant increase in alpha-2-macroglobulin and C-reactive protein concentrations was observed; this mobilization probably directly affected the albumin levels." (PMID 35371021, 2022).
childhood asthma (1 paper, 2025). "SQSTM1, HSPA5, and A2M which directly interact with RETN could serve as the potential therapeutic targets in childhood asthma." (PMID 41550933, 2025). "The resistin protein-protein interaction network analysis further suggests that SQSTM1, HSPA5 and A2M might serve as the potential therapeutic targets in childhood asthma." (PMID 41550933, 2025).
chronic kidney disease (1 paper, 2021). Impairment of the renal function secondary to chronic kidney damage persisting for three or more months. "We thus further investigated whether the activated α2M* was increased in our non-diabetic model of chronic kidney disease, 5/6 nephrectomy in CD1 mice, by IHC (ethics approval number 16-07-27)." (PMID 34572299, 2021).
chronic obstructive pulmonary disease (1 paper, 2025). A chronic and progressive lung disorder characterized by the loss of elasticity of the bronchial tree and the air sacs, destruction of the air sacs wall, thickening of the bronchial wall, and mucous accumulation in the bronchial tree. "According to research reports, the expression of A2M is decreased in the lung tissue and peripheral blood of patients with COPD (Chronic Obstructive Pulmonary Disease)." (PMID 41044788, 2025).
Clear Cell Renal Cell Carcinoma (1 paper, 2025). "However, little is known about the role of A2M in clear cell renal cell carcinoma (ccRCC)." (PMID 40740229, 2025).
cutaneous skin melanoma (1 paper, 2021). "We demonstrated that LINC00987 and A2M could be consistently regarded as protective factors in BRCA, kidney renal clear cell carcinoma, LUAD, sarcoma (SARC), cutaneous skin melanoma (SKCM), and UCEC; however, both were revealed to be risk factors for mesothelioma (MESO)." (PMID 33987201, 2021).
dengue (1 paper, 2012). "Other acute phase proteins that were elevated in dengue patients included C-reactive protein (CRP), alpha-2 macroglobulin (A2M) and ferritin (FT), while serum amyloid P (SAP), pro-calcitonin (PCT), tissue plasminogen activator (t-PA) and fibrinogen (FB) remained unchanged (not shown)." (PMID 23209847, 2012).
dental caries (1 paper, 2018). The decay of a tooth, in which it becomes softened, discolored, and/or porous. "As a result of MRM, protein S100 A9, protein S100 P, coronin 1A and alpha-2-macroglobulin were shared in HDC vs NDC and HDC vs LDC with higher expression levels in HDC group, indicating their potential diagnostic values in the childhood dental caries." (PMID 29351798, 2018).
depression (1 paper, 2020). "Together, this evidence supports a role of A2M in depression, but further studies are needed." (PMID 32699209, 2020).
Ehlers-Danlos syndrome (1 paper, 2008). The Ehlers–Danlos syndromes (EDS) are a clinically and genetically heterogeneous group of heritable connective tissue disorders (HCTDs) characterized by joint hypermobility, skin hyperextensibility, and tissue fragility. "Interestingly, the candidate with the lowest associated P-value is the Alpha-2-macroglobulin precursor (A2M), whose absence was previously reported in a patient with Ehlers-Danlos syndrome." (PMID 18369433, 2008).
endometrial cancer (1 paper, 2020). Primary or metastatic malignant neoplasm involving the endometrium (mucous membrane that lines the endometrial cavity). "We also assessed A2M protein expression in endometrial cancer using the Human Protein Atlas; this demonstrated “strong” A2M expression in 3/11 endometrial cancers." (PMID 32927694, 2020).
endometrial tumours (1 paper, 2020). "In our rat study, A2M expression was significantly reduced in endometrial tumours from the HFD compared to NCD group." (PMID 32927694, 2020).
hepatitis B infection (1 paper, 2015). "Many data have reported that α2M is overexpressed in HCC with the background of hepatitis B infection and the increased serological α2M is associated with HCC in humans, identifying α2M as a cytochemical marker for the diagnosis of HCC." (PMID 25958313, 2015).
hookworm infection (1 paper, 2012). "To determine the association of acute-phase proteins with hookworm infection, we measured the plasma levels of α-2M, CRP, haptoglobin, and SAA in INF and UN individuals." (PMID 23056659, 2012).
hypercoagulable (1 paper, 2020). "Similarly, hyperinsulinemia has been described as a hypercoagulable state, in part due to this increased thrombotic activity and the increased presence of alpha-2-macroglobulin." (PMID 32596266, 2020).
Hyperinsulinemia (1 paper, 2020). An increased concentration of insulin in the blood. "Alpha-2-macroglobulin is a known factor in coagulation, and thus its increase in the hyperinsulinemic hoof could be accounted for due to the tissue damage and inflammation during hyperinsulinemia-induced laminitis." (PMID 32596266, 2020).
hyperlipidemia (1 paper, 2021). "Importantly, A2M, APP, CLU, IGF2 and PLAU are not among the hyperlipidemia associated genes, they are retrieved only after obtaining the disease module with DIAMOND." (PMID 34824199, 2021).
influenza (1 paper, 2021). An acute viral infection of the respiratory tract, occurring in isolated cases, in epidemics, or in pandemics; it is caused by serologically different strains of viruses (influenzaviruses) designated A, B, and C, has a 3-day incubation period, and usually lasts for 3 to 10 days. "Interestingly, alpha-2-macroglobulin, an endogenous protein present in human saliva, nasal secretions, and blood, and also found to be elevated in poly(I:C) MSC-EVs, was shown to possess broad-spectrum anti-influenza activity." (PMID 34109180, 2021).
insomnia (1 paper, 2021). A sleep disorder characterized by difficulty in falling asleep and/or remaining asleep. "On the other hand, through Western blot experiments, we verified that the expression of FGG, FGB, FGA, APOB, F2, and HP was upregulated in insomnia patients with wakefulness compared with the control, while the expression of A2M, AHSG, and APOA1 was downregulated." (PMID 33511209, 2021).
Insulin resistance (1 paper, 2021). Increased resistance towards insulin, that is, diminished effectiveness of insulin in reducing blood glucose levels. "In previous works, an increased level of a cardiac form of α2M (c- α2M) in patients with insulin resistance was found, which was expressed in human and rat hearts." (PMID 34203120, 2021). "Although a high level of plasma α2M has also been found in patients with insulin resistance in a large cohort, its role in this process is not clearly established yet." (PMID 34203120, 2021).
intrahepatic cholangiocarcinoma (1 paper, 2024). A carcinoma that arises from the intrahepatic bile duct epithelium in any site of the intrahepatic biliary tree. "Zhang and collaborators described A2M downregulation in intrahepatic cholangiocarcinoma (ICC) compared to normal bile duct tissue, suggesting this gene’s potential utility as an adverse prognostic factor." (PMID 38612805, 2024).
iron overload (1 paper, 2025). "Present research suggested that altered expressions of HAMP, HP and A2M genes might have contributed to induce iron overload in PCOS patients." (PMID 40057801, 2025).
kidney cancer (1 paper, 2024). Primary or metastatic malignant neoplasm involving the kidney. "SerpinA3, as well as A2M, alpha-1-acid glycoprotein 2, are considered candidate biomarkers of various cancers, including kidney cancer." (PMID 39896931, 2024).
lupus nephritis (1 paper, 2023). Glomerulonephritis in the context of systemic lupus erythematosus. "As a known marker of glomerular permselectivity, A2M protein is a nonspecific protease inhibitor and it has been identified as a high-quality urinary biomarker and a strategy for evaluating disease progression of lupus nephritis." (PMID 37033921, 2023).
malaria (1 paper, 2020). Malaria is a serious and sometimes fatal disease caused by a parasite that commonly infects a certain type of mosquito which feeds on humans. "The data suggest that binding of non-immune IgM and α2M is higher in SM than in UM, consistent with a role for these phenotypes in malaria pathogenesis." (PMID 33032607, 2020).
meningioma (1 paper, 2014). A generally slow growing tumor attached to the dura mater. "Identified proteins like vimentin, alpha-2-macroglobulin, apolipoprotein B and A-I and antithrombin-III, which exhibited a sequential increase in different malignancy grades of meningiomas, could serve as potential predictive markers." (PMID 25413266, 2014).
meningitis (1 paper, 2025). A disorder characterized by acute inflammation of the meninges of the brain and/or spinal cord. "A2M, ADA2, and PDGFB, as cytokine receptors, displayed higher or lower levels compared to the other three meningitis types." (PMID 41181321, 2025). "Notably, 35 were upregulated compared to controls, particularly A2M and ADA2, which were more upregulated than in other meningitis types." (PMID 41181321, 2025).
metastatic cancer (1 paper, 2023). A carcinoma which has spread from the original site of growth to another anatomic site. "However, a decrease in the level of serum alpha-2-macroglobulin was observed in metastatic cancer of the rectum and colon." (PMID 37509426, 2023).
Neurodegeneration (1 paper, 2009). Progressive loss of neural cells and tissue. "In light of our findings, we propose a novel possible mechanism where Dpl-induced cerebellar neurodegeneration may be due to withdrawal of natural inhibitor(s) of metalloproteinases, such as α1I3 and α2M." (PMID 19536284, 2009).
oral cancer (1 paper, 2021). "For instance, increased expression of alpha-2-macroglobulin, haptoglobin, and mucin-5B on oral cancer-derived sEVs could serve as biomarkers for oral cancer diagnosis." (PMID 33791224, 2021).
osteonecrosis of the (1 paper, 2019). "A study included μCT and histological findings suggested that elevated α2M serum level is suitable as an indicative biomarker for early GC‐induced osteonecrosis of the femoral head (ONFH) in rodents, and α2M plays a role in the host reparative response to GC‐associated effects." (PMID 31243924, 2019).
Peptic ulcer (1 paper, 2021). The term peptic ulcer refers to acid peptic injury of the digestive tract, resulting in mucosal break reaching the submucosa. "In short, it can be stated that inflammation caused by peptic ulcer can increase the serum levels of proteinase inhibitors and anti‐inflammatory substances, such as α‐2M." (PMID 34405561, 2021).
Pre-eclampsia (1 paper, 2023). "Pre-eclampsia (PE) is one of the leading causes of maternal and fetal morbidity/mortality during pregnancy, and alpha-2-macroglobulin (A2M) is associated with inflammatory signaling; however, the pathophysiological mechanism by which A2M is involved in PE development is not yet understood." (PMID 36894970, 2023).
renal fibrosis (1 paper, 2021). A final common manifestation of a wide variety of chronic kidney diseases characterized by glomerulosclerosis and tubulointerstitial fibrosis. "α2M was also increased in two models of renal fibrosis (puromycin aminonucleoside nephrosis and 5/6 nephrectomy), particularly in glomeruli, with expression noted to increase as fibrosis progressed." (PMID 34572299, 2021).
Schistosoma haematobium infection (1 paper, 2025). "Machine learning emphasized SYNPO2, CD276, α2M, LCAT, and hnRNPM as the most discriminating biomarkers for Schistosoma haematobium infection." (PMID 40853910, 2025).
schistosomiasis (1 paper, 2025). An infectious disease caused by parasitic trematodes of the genus Schistosoma that colonize human blood vessels and release eggs that can cause granulomatous reactions leading to acute (swimmer's itch or acute schistosomiasis syndrome) or chronic disease. "Such processes are not unique to schistosomiasis but are also observed in bacterial infections such as UTIs, where systemic inflammation and endothelial repair mechanisms could lead to α2M upregulation." (PMID 40853910, 2025).
schizophrenia (1 paper, 2012). A major psychotic disorder characterized by abnormalities in the perception or expression of reality. "This showed that 9 of the analytes (C-reactive protein, cortisol, resistin, TIMP-1, chromogranin A, VEGF, thrombopoetin, alpha-2 macroglobulin, and glutathione S-transferase) were also found to be reproducibly altered between schizophrenia and control subjects in serum." (PMID 23118852, 2012).
senile osteoporosis (1 paper, 2023). "This phenomenon is consistent with data showing downregulation of A2M drives expansion of the Lin−LEPR+ SSPC pool and skews their bifurcation toward adipogenesis, which reconciles observed skeletal pathology in mice and humans afflicted with senile osteoporosis." (PMID 37965574, 2023).
Senile plaques (1 paper, 2023). Senile plaques are extracellular deposits of amyloid in the gray matter of the brain. "AD cortical senile plaques display strong IL-6 immunoreactivity, which is functionally related to alpha-2-macroglobulin." (PMID 36936500, 2023).
thoracic outlet syndrome (1 paper, 2022). A syndrome resulting from the compression of the blood vessels or nerves in the space between the clavicle and first rib (thoracic outlet). "Recently, the effectiveness of alpha 2 macroglobulin (A2M), a plasma protein, was investigated in the neurogenic thoracic outlet syndrome and other forms of cervical brachial syndrome." (PMID 35431971, 2022).
Thromboembolism (1 paper, 2010). The formation of a blood clot inside a blood vessel that subsequently travels through the blood stream from the site where it formed to another location in the body, generally leading to vascular occlusion at the distant site. "A2M has also been implicated in hemostasis as a regulator of thrombin and in the development of thromboembolism in children." (PMID 20579363, 2010).
tick-borne encephalitis (1 paper, 2017). Tick-borne encephalitis is caused by an arbovirus of the Flaviviridae family (tick-borne encephalitis virus, TBEV), transmitted principally by the bite of the Ixodes ricinus tick. "Using STRING we found that IL10 interacted physically with alpha-2-macroglobulin (A2M) that was also found to be elevated in patients with the meningeal and focal forms of tick-borne encephalitis." (PMID 29297316, 2017).